CRP (C-reactive protein)
Diseases named in the same sentence as CRP in open-access papers (continued):
Sharing a sentence is not in itself a finding about the gene and the disease.
depression (continued). "In conclusion, this systematic review provides robust evidence about the potential role of CRP and its blood levels in depression." (PMID 35163538, 2022). "The odds of depression increased by 2% (95% CI = 1–4%) for every unit (mg/L) increase of CRP and nearly doubled for men with CRP ≥ 3 mg/L vs. < 1 mg/L." (PMID 35163538, 2022). "Levels of C-reactive protein (CRP), a peripheral inflammatory indicator, correlated positively with the PHQ-9 total score of patients who presented symptoms of depression, suggesting a potential inflammatory pathway underlying these symptoms." (PMID 36033820, 2022). "DII has been reported to have association with numerous plasma inflammatory markers (CRP and IL6) and multiple health outcomes (stoke, depression, CVDs, metabolic risk markers, cancer and all-cause and specific-cause mortality)." (PMID 35745147, 2022). "In line with this, CRP inhibits leptin from binding to its receptor in mice, again implicating central leptin resistance as a possible pathological mechanism for depression." (PMID 35633817, 2022). "Some studies support the idea that there is a close relationship between inflammation and depression, as CRP levels were correlated with depression scores at subsequent follow-up time-points." (PMID 36422176, 2022). "In a meta-analysis that compared 5166 patients with depression and 5083 controls, patients with depression exhibited a significantly higher pro-inflammatory state (i.e., higher levels in CRP, L-3, IL-6, IL-12, IL-18, sIL-2R, and TNFα) than controls." (PMID 35682203, 2022). "Serum 25(OH)D, intact parathyroid hormone (iPTH), interlukin (IL)-1β, IL-6, high-sensitivity C-reactive protein (hs-CRP) and depression severity (Beck Depression Inventory-II) (BDI-II)) were initially and finally assessed." (PMID 36368945, 2022). "Conversely, higher CRP levels at baseline have also been shown to distinguish between RA patients who would go on to develop depression." (PMID 36422176, 2022). "The first cluster consisted of all patient-reported psychoneurological symptoms (poor sleep quality, depression, anxiety, fatigue, and oral pain) together with an inflammation marker (CRP) and stress marker (the cortisol slope)." (PMID 36290836, 2022). "This contradicts a recent ELSA study that identified a relationship between pre-pandemic CRP and depression during the pandemic among older adults." (PMID 36198766, 2022). "Increased pro-inflammatory markers [IL-6, IL-1β, TNF-α, and C-reactive protein (CRP)] occur in individuals with depression, supported by reports of anti-depressant effects of TNF-α antagonists." (PMID 35492581, 2022). "CRP, especially, has been the subject of much attention as a peripheral marker of inflammation that seems to be correlated with depression incidence and severity." (PMID 35618889, 2022). "Patients with depression have been shown to have elevated levels of C-reactive protein (CRP) and pro-inflammatory cytokines, such as tissue necrosis factor, interleukin-1, interleukin-2, and interleukin-6." (PMID 35233310, 2022). "On the other hand, our unadjusted model did show that PHQ-9 was significantly associated with CRP levels (β = 0.125) and our effect size was comparable to that reported in the UK Biobank study of depression and CRP (β = 0.144) by Pitharouli and colleagues." (PMID 35821205, 2022). "The most common cytokines associated with poor psychological outcomes involving PTSD and/or depression in the chronic mTBI population were IL-6, TNFα, IL-10, and CRP." (PMID 35053845, 2022). "For the subgroup of 84 patients, significant Pearson’s correlations were found between Δlog CRP values and depression history (r = 0.299, p = 0.003), troponin (r = −0.230, p = 0.018), and antidepressant use (r = 0.385, p < 0.001)." (PMID 35566447, 2022). "The estimated effect of smoking on depression remained significant after adjusting for the effect of CRP (OR = 2.00; 95% CI : 1.61–2.48; p = 3.5 * 10–8)." (PMID 36057695, 2022).
depression (continued). "A preponderance of studies has established a positive association between proinflammatory cytokines (including C-Reactive Protein (CRP), Interleukin-1 (IL-1), and Interleukin-6 (IL-6)) and depression, of which apathy is an important component." (PMID 35742625, 2022). "A prospective study with a follow-up period of 12 years also suggested a predictive role of proinflammatory cytokines including C-reactive protein (CRP) and IL-6, in depression." (PMID 36093196, 2022). "CRP levels were significantly higher in patients with depression than in the control group (2.4 mg/L compared with 2.1 mg/L, p < 0.001)." (PMID 35163538, 2022). "CRP explained only 4% of the effect of change in the DII on depression symptoms score among pre-menopausal women (p-trend = 0.024) and 5% among post-menopausal women (p-trend = 0.006) in the age-adjusted model." (PMID 35565951, 2022). "ACE inhibitors can, therefore, effectively reduce inflammatory mediators, such as IL-6 and CRP, and play a role in improving depression, anxiety, and other adverse emotions." (PMID 35527821, 2022). "The prospective cohort study assessed serum CRP, IL-6, and cognitive symptoms of depression over a long period of time, averaging 11.8 years." (PMID 35163141, 2022). "We also tested the mediating role of inflammation, as assessed by CRP levels, on the association of the DII and depression in both population groups." (PMID 35565951, 2022). "A similar coupling of depression with elevated CRP and IL-6 has also been found among female adolescents who had experienced childhood adversity." (PMID 34990745, 2022). "A meta-analysis suggested that patients with depression showed elevated levels of pro-inflammatory cytokines and C-reactive protein (CRP)." (PMID 36235852, 2022). "Initially, basic immune factors such as C-reactive protein (CRP), interleukin 1 (IL-1) and interleukin 6 (IL-6) were found to be elevated in depression." (PMID 35757204, 2022). "Finally, stable elevated CRP levels were associated with increased risk for late-life depression symptoms and the occurrence of multiple depressive episodes seems to improve later CRP levels, maybe by increasing the risk for cardiovascular and metabolic disease." (PMID 35163538, 2022). "Due to the nature of our study design, we were only able to assess recent dietary intake, CRP, and depression levels." (PMID 35565951, 2022). "Another cross-sectional study, based on the KNHANES, aimed at investigating the sex difference in the association between hs-CRP levels and depression, recruited 5483 Korean adults (2373 men and 3110 women) assessed with PHQ-9 (cut-off for depression > 10)." (PMID 35163538, 2022). "Studies have indicated that a high Dietary Inflammatory Index (DII) score is associated with high C-reactive protein (CRP) levels and depression." (PMID 35565951, 2022). "Apparently, neutrophil and eosinophil granulocytes as well as CRP have a more general role in major psychiatric disorders as these parameters were altered in both depression and schizophrenia." (PMID 35379263, 2022). "Cross-sectional study data revealed that elevated levels of CRP were relevant to a high prevalence of depression in diabetes patients with high BMIs." (PMID 36235852, 2022). "Recent meta-analyses have revealed high concentrations of IL-6, TNF-α and CRP in depressed patients as compared with healthy controls, but only TNF-α demonstrated a genetic association with major depressive disorders (MDD) among pro-inflammatory cytokines." (PMID 36615742, 2022). "C-Reactive Protein (CRP) is a widely-studied inflammatory cytokine whose serum concentrations have been correlated with depression severity." (PMID 35618889, 2022). "Duration of education, LB-IADL, MMSE, MNA-SF, sleep time, sleep quality, CFS, sedimentation rate, leukocyte count, and CRP were found to be significant predictive factors for higher depression scores." (PMID 36326335, 2022).
depression (continued). "CES-D The Center for Epidemiologic Studies Depression Scale; IADLs Instrumental Activities of Daily Living; IL-6 Interleukin-6; hsCRP High sensitivity C-reactive protein." (PMID 35279110, 2022). "Further studies have found elevated levels of CRP in participants with atypical depression when compared to anxious, melancholic, psychotic, and unspecified depression, diagnosed using the SCID for DSM-V." (PMID 35146459, 2022). "In the first cluster (red), “depression” appears most frequently as the main keyword, followed by “inflammation”, “stress”, “anxiety”, “interleukine-6”, “C-reactive protein”, and “cortisol”." (PMID 36186850, 2022). "Third, the relationships of serum cytokines, CRP, and cortisol with the severity of depression and anhedonia were examined in MDD." (PMID 36090246, 2022). "The elevated CRP group (>3 mg/L) showed greater symptom connectivity, concentration, psychomotor difficulties, and treatment-resistant depression." (PMID 35163538, 2022). "The Dietary Inflammatory Index (DII), validated in previous depression studies, correlates with elevated inflammatory markers such as CRP, IL-6 and TNF-α." (PMID 35172770, 2022). "A multivariable linear regression analysis that included age, BMI, headache frequency, and the severity of anxiety (GAD-9 score) and depression (PHQ-9 score) revealed that there was a significant positive linear relationship between CRP levels and BMI." (PMID 36313504, 2022). "Previously, it was shown that, in RA, IL-10 levels are positively correlated with RF, anti-CCP, and CRP, while there is also a well-established link between depression and elevated IL-10." (PMID 35330475, 2022). "We performed inverse variance weighted Mendelian randomization (MR) analyses using recently published summary-level GWAS data for lifetime smoking index, CRP levels, and depression." (PMID 36057695, 2022). "Individuals with high CRP levels had a significantly higher rate of depression compared to the others." (PMID 35163538, 2022). "A meta-analysis on twelve studies regarding various psychiatric diseases – from depression and AD to schizophrenia – also revealed that supplementation of probiotics decreased levels of CRP and malondialdehyde among neuropsychiatric patients." (PMID 35757204, 2022). "Recent studies reported elevated serum CRP concentrations in the subjects with major depressive disorder (MDD) and especially in those who were resistant to treatment." (PMID 36368945, 2022). "In a previous study, CRP levels were found to be moderately correlated with BD in patients with depression and euthymia but highly correlated with BD in patients with mania." (PMID 36551802, 2022). "The level of Interleukin 6 (IL-6), C-reactive protein (CRP) or other pro-inflammatory biomarkers can be enhanced by pro-inflammatory diets, and further raise the risk for the development of depression." (PMID 36159493, 2022). "Unfortunately, among anti-inflammatory strategies, only patients with depression and high initial inflammation or high baseline CRP levels showed significant antidepressant effects." (PMID 36186850, 2022). "CRP DNAm scores associated with more brain regions and with larger effect sizes than serum CRP, in the context of depression." (PMID 36277463, 2022). "In this study, we assessed the impact of RIF on serum CRP and faecal calprotectin (fCal), as well as disease activity indices, quality of life, and depression scales in patients diagnosed with IBD." (PMID 35462542, 2022). "A cohort study selected 1508 young individuals who were evaluated regarding the incidence of low-grade inflammation (i.e., CRP < 3 mg/L at baseline) and the depressive state using the Beck Depression Inventory (BDI)." (PMID 35163538, 2022). "Adjusting for a range of covariates, we identified lifetime depression before MI onset as an independent predictor of a smaller decrease over time in Δcat-CRP and Δlog CRP with similar effect sizes." (PMID 35566447, 2022).
depression (continued). "In CSF, CRP was associated only with anxiety while in serum, IL-8, MIP-1α, TARC and VEGF-D were associated only with depression." (PMID 35643540, 2022). "In the chronic inflammatory state associated with stress, Interleukin (IL)-1beta, Tumor Necrosis Factor (TNF)-alpha and IL-6 have been reported to be the most represented cytokines; Serum C-Reactive Protein, IL-1 and IL-6 were the most prevalent in depression." (PMID 35323251, 2022). "It has been demonstrated that impaired functional connectivity between dorsal caudate and dlPFC is strongly correlated with inflammation as measured by C-reactive protein in patients with major depressive disorder." (PMID 36353137, 2022). "During follow-up, cognitive decline was independently associated with more pronounced inflammatory activity (in terms of C-reactive protein) and with depression (as assessed using the BDI)." (PMID 35885032, 2022). "Dietary patterns dominated by dietary fiber and vitamins were negatively correlated with depression and CRP." (PMID 36713916, 2022). "The most significant changes were found for two pro-inflammatory factors: IL-6 and CRP, which were increased in patients with depression compared to healthy controls." (PMID 35163141, 2022). "Only a few studies investigated a priori chosen proteins, such as sICAM-1, IL-10, CRP, and reported associations with NPS in general as well as with apathy and depression." (PMID 35326481, 2022). "A systematic review was performed for the topics of ‘CRP’ and ‘depression’ using the PubMed database from inception to December 2021." (PMID 35163538, 2022). "Our research strongly suggests that future studies examining the effect of inflammatory cytokines on depression should broaden their scope beyond CRP." (PMID 36057695, 2022). "Patients with depression show higher levels of peripheral inflammation markers such as C-reactive protein (CRP), and cytokines compared with controls." (PMID 35036964, 2022). "Compared to depressed men, depressed women have higher levels of IL-6, after controlling for BMI, and in a study of 231 men and women with major depressive disorder, higher CRP levels correlated with severity of depression in women but not men." (PMID 36304737, 2022). "A significant proportion of people with depression have clear signs of inflammation in their blood, with an increase in C-reactive protein and pro-inflammatory cytokines." (PMID 35409300, 2022). "For example, in depression, levels of C-reactive protein (CRP) are higher in TRD compared with those who respond to antidepressant treatment." (PMID 34257409, 2022). "Using CRP > 3 mg/L as a cut-off value, approximately 40% of cases with depression had increased immune cell counts, increased inflammatory proteins and increased symptom severity scores, compared to the remaining 60% of cases without inflammation." (PMID 35409300, 2022). "In line with this, in a longitudinal Australian cohort (N = 1,692; 55–85 years), the inflammatory markers interleukin-6 (IL-6) and CRP explained 10.9 and 8.1% of the risk of incident CVD hospitalizations associated with depression, respectively." (PMID 36311535, 2022). "Higher serum CRP levels in women were significantly correlated with Montgomery Aasberg Depression Rating Scale symptom severity, severity on observed mood, cognitive symptoms, interest-activity, and suicidality." (PMID 35163141, 2022). "For example, increased levels of C-reactive protein (CRP), interleukine-6 (IL-6) and tumor necrosis factor-α have been repeatedly observed in patients with depression." (PMID 36447174, 2022). "This work provides robust evidence about the potential role of CRP and its blood levels in depressive disorders." (PMID 35163538, 2022). "For example, clinical trials of anti-inflammatory medications for depressive disorder should pre-select subgroups of patients with raised inflammatory markers, such as peripheral CRP, as they are more likely to benefit from these treatments." (PMID 35511258, 2022).
depression (continued). "In the last few years, numerous studies further revealed that besides IFN-α, the proinflammatory cytokines IL-6 and TNF-α and increased blood levels of the C-reactive protein (CRP), in particular, are associated with depressive disorders." (PMID 36358455, 2022). "After controlling for confounders, the levels of CRP in subjects with depression were higher than that in healthy controls." (PMID 34421539, 2021). "A strong case is presented for the systemic inflammatory marker CRP, whose high concentrations distinguished those reporting the highest levels of anxiety and depression from all others." (PMID 33301421, 2021). "After treatment for mania, CRP levels moderately decreased, but this decrease was slight after treatment for depression." (PMID 33672126, 2021). "Results hold implications for the diagnosis of CM-related CRP elevation and (potentially) depression." (PMID 34867491, 2021). "A longitudinal study found that patients who experienced early life stress followed by depression had significantly higher CRP level than those who only suffered from depression and did not experience early life stress." (PMID 34890365, 2021). "Another study found that decreased apolipoprotein A1 and increased C-reactive protein (CRP) were associated with severe motor symptoms, depression, and sleep disorders." (PMID 34867224, 2021). "Third, based on the results of multiple test corrections, we detected several suggestive associations (P < 0.05) for the effect of interaction between CRP and gut microbiome on the risks of anxiety and depression." (PMID 34481527, 2021). "Prospective researches also show that depression can predict the later level changes of IL-6 and CRP." (PMID 34054732, 2021). "More precisely, patients with elevated CRP or presence of GE on T1-weighted MRI-imaging were more likely to score higher on depression scales BDI and SCL90RD." (PMID 34764926, 2021). "After taking into account CRP and sIL-2Rα, increased IL-6 levels were associated with increased risk for both schizophrenia (IVW OR=1.26; 95% C.I., 1.05-1.52) and major depression (IVW OR=1.08; 95% C.I., 1.03-1.12)." (PMID 34280516, 2021). "Multivariate logistic regression models were used to predict the onset of depression based on C-reactive protein (CRP) and white blood cell count (WBC)." (PMID 33500534, 2021). "We tested associations of CRP and WBC on new onset of depression in separate multivariate logistic regression models." (PMID 33500534, 2021). "In the present study, many anti-depressant targets of EMO against depression were associated with the inflammatory response such as IL6, TNF, IL10, CRP, IL1B, CTLA4, ALB and IL2." (PMID 34051074, 2021). "Using CRP as a continuous variable, the adjusted OR for depression per-unit increase in log CRP was 1·09 (95% CI, 1·06–1·11)." (PMID 34505025, 2021). "Depression displays strong relation to an increase in peripheral inflammatory mediators, such as IL-6, C-reactive protein and TNF-α." (PMID 34200513, 2021). "This was evident in a sample of obese women, where higher overall C-reactive protein (CRP) levels during pregnancy were predicted by both history of depression diagnosis prior to pregnancy and higher depressive symptoms during pregnancy." (PMID 34877551, 2021). "In this study, data from UK biobank were applied to evaluate the influence of interactions between CRP and gut microbiome on anxiety and depression." (PMID 34481527, 2021). "Elevated levels of various inflammatory biomarkers, such as IL-6 and TNF-α, and increased high-sensitivity C-reactive protein (CRP) concentrations were found to be present in patients with mild to moderate depression six months following stroke." (PMID 34471414, 2021). "Concentrations of C-reactive protein (CRP), interleukin 6 (IL-6) and other inflammatory markers are elevated in people with depression and anxiety compared to controls, but evidence for disorder-specificity, linearity and potential causality is sparse." (PMID 34505025, 2021).